IL6 (interleukin 6)
Diseases named in the same sentence as IL6 in open-access papers (continued):
Sharing a sentence is not in itself a finding about the gene and the disease.
Hyperglycemia (continued). "Correlations with measures of hyperglycemia, adiposity, lipids, blood pressure and inflammation were generally weaker, exceptions being FABP4 and ADM which correlated with body fat content (r = 0.75 and r = 0.69, respectively), and IL6 which correlated with CRP (r = 0.63) and WBC (r = 0.62)." (PMID 33279861, 2021). "Among the biological factors are hyperglycemia, hyperinsulinemia, overproduction of insulin-like growth factor-1 (IGF-1), increased expression of the IGF-1 receptor, and increased secretion of inflammatory cytokines, such as interleukin 6 (IL-6) and tumor necrosis factor alpha (TNF-α)." (PMID 32473631, 2020). "Furthermore, stimulation with both rIL-17 and high glucose was more effective in increasing the expression of inflammatory cytokines IL-6 and TNFα and the chemokine CCL2 than either condition alone, suggesting IL-17 and hyperglycaemia synergistically promote diabetic podocyte injury." (PMID 30783187, 2019). "Similarly, treating mice with an IL-6 neutralizing antibody prior to exhaustive exercise did not negate the protective effect of exercise against olanzapine-induced hyperglycemia." (PMID 29335597, 2018). "Our findings provide evidence that a single bout of exhaustive exercise protects against acute olanzapine-induced hyperglycemia and that IL-6 is neither sufficient, nor required for exercise to protect against increases in blood glucose with olanzapine treatment." (PMID 29335597, 2018). "Moreover, hyperglycemia can induce the expression of several proinflammatory cytokines, such as interferon gamma (INF-γ), interleukin-6 (IL-6), and tumor necrosis factor-alpha (TNF-α), leading to the development of a chronic subclinical inflammatory status in DM." (PMID 26770985, 2016). "Chronic hyperglycemia modulates immune responses and triggers inflammation through the activation of Toll-like receptors (TLRs), leading to an increase in the proinflammatory cytokines, IL1, IL6, TNFα and interferon γ(IFNγ), and a decrease in the levels of interleukin 10 (IL10)." (PMID 24260283, 2013). "Second, because there was a weak correlation between the APACHE II score and glucose level on ICU admission, we could not completely deny that IL-6-related hyperglycemia might be an epiphenomenon of severe illness." (PMID 22494810, 2012). "To test this hypothesis, we quantified the gene expression of macrophage-secreted cytokines (IL-1β, IL-6, TNF-α, IL-10) and chemokines (CCL2) in the lacrimal gland, conjunctiva and cornea of non-diabetic normoglycemic mice and diabetic mice with 7, 14, and 28 days of hyperglycemia." (PMID 39749321, 2024). "While serum insulin was not increased in exercised IL-6−/− mice treated with olanzapine, the rise in blood glucose was prevented in these animals providing evidence that protection against olanzapine-induced hyperglycemia with exercise is not mediated by increases in circulating insulin." (PMID 29335597, 2018). "Specifically, hyperglycemia may facilitate the synthesis of advanced glycation end products (AGEs) that induce oxidative stress via RAGE, activating NF-κB that initiates and regulates inflammation by synthesizing proinflammatory cytokines, including TNF-α, IL-1β, and IL-6." (PMID 26074994, 2015). "Therefore, it is possible to suggest that hyperglycemia promotes the development of a chronic low grade inflammation in renal parenchyma, characterized by increased levels of proinflammatory cytokines INF-γ, TNF-α, and IL-6 levels, which may be involved in the pathogenesis of diabetic nephropathy." (PMID 26770985, 2016). "For instance, hyperglycemia per se, regardless of the presence/absence of concurrent endotoxemic insult, depressed the expression of TNF-α mRNA, but augmented the IL-1β and IL-6 mRNA expression in MLNs." (PMID 26207186, 2015).
Hyperglycemia (continued). "This lower level of plasma IL-6 was correlated with the 64% lower post-meal hyperglycemia but not with the higher postprandial insulin levels suggesting that a decrease in post-meal hyperglycemia and not hyperinsulinemia directly, may be responsible for the lower plasma IL-6 levels." (PMID 23776669, 2013). "The animals with MS presented a dysregulation in the negative feedback mechanism between IL-6 and NA (and probably also CTC) that can contribute to the systemic low-grade inflammation and/or hyperglycaemia of MS." (PMID 21599899, 2011). "Lastly, a significant decrease in the expression of IL-6, TNF-α, and CCL2 was noted in the cornea at 7 days after hyperglycemia, whereas no significant alterations in the expression of these genes could be noted at 14 or 28 days of hyperglycemia." (PMID 39749321, 2024). "Therefore, hyperglycemia and hypoxia have a negative effect on inflammation as they upregulate the gene expression of the inflammatory cytokines TNF-α, IL-6 and IL-1 in activated macrophages." (PMID 31415598, 2019). "Our findings show that mice in the CIT + HFD and STZ + HFD groups had increased levels of systemic pro-inflammatory IL-6 after 18 weeks, but not STZ + CON mice, suggesting that high-fat feeding is more likely to contribute to systemic inflammation over hyperglycemia." (PMID 30348168, 2018).
Anxiety (588 papers, 2006 to 2026). Intense feelings of nervousness, tension, or panic often arise in response to interpersonal stresses. "For instance, IL-6 has been implicated in exacerbating hypervigilance and somatic anxiety symptoms by modulating neural activity in the hypothalamus and amygdala." (PMID 40218134, 2025). "Spearman correlation analysis showed that the levels of IL-6 were positively associated with the anxiety score (Spearman’s rho = .230, p = .021), obsessive–compulsive symptoms (Spearman’s rho = .201, p = .042)." (PMID 39757257, 2025). "This again caused anxiety behaviour with induced activation of IL-6, TNF-α and IL-1β expression, indicating colitis." (PMID 41462928, 2025). "This study investigated the associations between responses to competitive anxiety and salivary biomarkers-cortisol (sCort), interleukin-6 (sIL-6), and tumor necrosis factor-alpha (sTNF-α)-in elite female karate athletes during competition." (PMID 42238605, 2025). "IL-6 is a key cytokine in systemic inflammation and is associated with anxiety and cognitive impairment in both clinical and experimental models." (PMID 40868917, 2025). "It is noteworthy to mention that even certain psychopathological conditions in mothers, such as peripartum depression and peripartum anxiety, have been revealed to be associated with increased serum levels of Interleukin-6, TNF- α, and IL-8." (PMID 40242671, 2025). "Additional variables related to aggressive, affiliative, and anxiety-like behaviors and their associations with (%ΔGlu) and cortisol, interleukin-6 (IL-6), and peripheral measures of systemic inflammation (C-reactive protein; CRP) were also examined." (PMID 40157907, 2025). "The levels of IL-6 exhibited a significant positive association with the anxiety score (Spearman’s rho = 0.230, p = 0.021) and OCS (Spearman’s rho = 0.201, p = 0.042)." (PMID 39757257, 2025). "Anxiety, sadness, and chronic stress are all mental health issues that are associated with elevated IL-6 saliva levels, which can be used as a marker of dysregulated immune-neuroendocrine function." (PMID 40728957, 2025). "Anxiety has also been associated with higher levels of circulating inflammatory markers (e.g., IL-6, CRP), which can enhance pain sensitivity and reduce pain modulation capacity." (PMID 41303122, 2025). "Mechanistically, the anti-anxiety action of quercetin is closely associated with the inhibition of interleukin-6 (IL-6) and interleukin-1β (IL-1β) expression in the hippocampus." (PMID 40520201, 2025). "Controls were not given psychological assessments, so it is unclear if the CSF IL‐6 and anxiety/frustration association is disease‐specific." (PMID 39317977, 2024). "Specifically, heightened C-reactive protein and interleukin-6 (IL-6) levels have been linked to the onset of depressive and anxiety symptoms, whereas remission is associated with the normalization of inflammatory markers." (PMID 39339649, 2024). "The HFD in rats induced anxiety-like behavior associated with neuroinflammation, overproduction of IL-1β and IL-6, cerebral oxidative stress, increased lipoperoxidation, inhibition of enzymatic and non-enzymatic antioxidants, and increased ROS levels." (PMID 38279738, 2024). "EPM classification reveals that higher anxiety-like behavior is associated with chronic neuroinflammation as Sus-EPM rats have high levels of both IL-6 and IL-10 in PFC." (PMID 37064304, 2023). "Growing evidence supports a positive association between anxiety and inflammatory cytokines, such as interleukin-6 and C-reactive protein, which are known to be elevated in individuals with frailty." (PMID 36908457, 2023). "This agrees with previous studies that demonstrated that anxiety-like behavior was associated with the increased mRNA expression of proinflammatory markers, including IL6, TNFα, NFkB, and MCP-1, in the hypothalamus and amygdala." (PMID 38201896, 2023).
Anxiety (continued). "Animal studies showed an increase in IL-6 levels with the associated anxiety in response to stress and a relationship between elevated IL-6 levels during pregnancy and increased risk of anxiety behaviors in the offspring." (PMID 37840785, 2023). "Anxiety, as well as (chemotherapy-induced) PN, has been associated with increased pro-inflammatory cytokines, such as IL-6." (PMID 35303166, 2022). "Gastrointestinal tract inflammation instigates the liberation of pro-inflammatory cytokines, and increase in tumor necrosis factor-alpha (TNF-α) and interleukin 6 (IL-6) cytokines is linked directly with anxiety-like manifestations." (PMID 35433746, 2022). "Conceivably, anxiety is induced by immune system activation and is associated with proinflammatory cytokines, such as interleukin (IL)-6." (PMID 33255406, 2020). "The influence of anxiety is due to a transcriptional pattern observed in animal models, in which monocytes are recruited that specifically depend on the increase of IL-6 in serum, once anxiety in stressful situations is caused." (PMID 31979305, 2020). "Increased levels of IL-1β and IL-6 are associated with increased stereotypy, impaired cognitive abilities, anxiety, and decreased social interactions." (PMID 32443651, 2020). "As expected, the results of our study showed a trend toward anxiety being associated with increased stimulated IL‐6 levels for healthy controls." (PMID 31199593, 2020). "Accordingly, a long-term HFD (16 weeks) has been shown to cause anxiety, increase corticosterone level, and increase inflammatory cytokines, such as interleukin-6, interleukin-1β, and tumor necrosis factor-α." (PMID 32209056, 2020). "In IL-6-deficient mice, the results have shown that this cytokine can affect emotional related behaviors, especially anxiety-related behaviors." (PMID 30678337, 2019). "Recent findings show that anxiety is associated with increased levels of interleukin-6 (IL-6) and associated with an increased risk for diseases with an inflammatory etiology." (PMID 30943938, 2019). "SAR, however, markedly diminished the duration spent in one square, indicating an anxiolytic effect mediated by PPARγ’s capacity to inhibit pro-inflammatory cytokines like TNF-α and IL-6, which are implicated in neuroinflammation-related anxiety and cognitive impairment." (PMID 40863337, 2025). "Similarly, difficulties in regulating positive emotions were associated with increased CRP and IL-6 levels and various symptoms, such as chronic fatigue, anxiety, and somatic complaints." (PMID 41333345, 2025). "As IL-6 is elevated because of chronic stress, it causes expanded recruitment of proinflammatory monocytes and heightens the expression of their related gene, which is associated with the development of anxiety." (PMID 39410900, 2025). "However, our findings also showed a positive association between IL-6 and anxiety, which contradicts the results of some previous studies." (PMID 39757257, 2025). "Numerous studies have found that high levels of serum IL-6 and IL-8 in cancer patients are significantly associated with anxiety and depressive states, and IL-6 and IL-8 have also been validated clinically to be associated with poorer responses to ICIs treatment." (PMID 40786522, 2025). "Cd exposure causes a rise in anxiety-like behavior and disorderly movement, disruption to spatial reference memory, Aβ plaque formation in mice brains, an increase in microglia expression in the brain, and elevates IL-6 levels in the cortex and serum." (PMID 40278152, 2025). "Emerging hypotheses propose that systemic inflammation—implicated in ADHD and anxiety through genetic variants in pathways like IL6 and TNF-α—may also contribute to oncogenic processes in HNC." (PMID 40182194, 2025). "Our results suggest that neuroinflammation with elevated CSF IL‐6 levels may be a common factor of psychiatric disorders that is associated with anxiety and frustration, the commonly observed symptoms in psychiatric disorders." (PMID 39317977, 2024).
Anxiety (continued). "Serum TNF-α and IL-6 levels in MSA patients may be associated with anxiety symptom; however, only TNF-α was shown to be a useful tool in distinguishing between MSA and HCs." (PMID 39295596, 2024). "Besides, pro-inflammatory cytokines such as TNF-α, and IL-6 were significantly associated with anxiety scores." (PMID 38902708, 2024). "Although correlation analysis found that IL-6 was linearly associated with multiple clinical variables, stepwise forward regression analysis found only HAMA had positive association with IL-6 level, which suggested that IL-6 had some effect on anxiety in MSA patients." (PMID 39295596, 2024). "The present study aimed to examine whether CSF IL‐6 levels are associated with anxiety and frustrative non‐reward." (PMID 39317977, 2024). "Consequently, both increased and decreased levels of IL-6 have been associated with stress and anxiety-related behaviors." (PMID 39065697, 2024). "We hypothesized that CSF IL‐6 is associated with psychiatric symptoms across psychiatric disorders, and examined whether CSF IL‐6 is associated with anxiety and frustration, which are common symptoms in psychiatric disorders and components of NVS." (PMID 39317977, 2024). "We found that high CSF IL‐6 levels were associated with anxiety and frustration across psychiatric disorders, which may be related to altered CBF of specific brain regions." (PMID 39317977, 2024). "In addition, the elevated TNF-α and IL-6 levels were associated with anxiety symptoms in MSA patients, and further studies with longitudinal and prospective designs from multiple centers and ethnic populations are required to verify these preliminary findings." (PMID 39295596, 2024). "Furthermore, anxiety triggers inflammatory processes by causing high levels of pro-inflammatory cytokines such as IL-6, IL-1β, and TNF-α." (PMID 39720795, 2024). "Taken together, high CSF IL‐6 levels associated with anxiety and frustration, may be related to altered rCBF of specific brain regions." (PMID 39317977, 2024). "Furthermore, inflammatory processes are triggered by anxiety, which is caused by high levels of pro-inflammatory cytokines such as IL-6, IL-1β and TNF-α." (PMID 38255283, 2024). "Moreover, anxiety is linked to the secretion of neuroendocrine and inflammatory parameters such as substance P (SP), interleukin (IL)-6 and IL-17, which are also related to itch." (PMID 36928456, 2023). "Additionally, IL-6 has been linked to mental illnesses such as anxiety, despair, and suicide ideation, and numerous studies have historically reported a correlation between IL-6 levels and suicidality both in adults and adolescents." (PMID 37371695, 2023). "It has been proposed that these sex differences in anxiety‐like behavior and reduced learning may be caused by enhanced expression of pro‐inflammatory molecules (TNFα, IL6) and neuroinflammation in the brain of aged female mice." (PMID 37675802, 2023). "Similarly, an animal study on obese rats reported decreased anxiety-like behaviour after DHA/EPA supplementation associated with a reduced plasma concentration of IL-6 and TNF-α, as well as suppressed TNF-α synthesis in the prefrontal cortex." (PMID 37240914, 2023). "In mice exposed to stressors that involve repeated social defeat, including the social-disruption (SDR) stressor used in this study, cytokines such as IL-1 and IL-6 are increased in the serum, peripheral organs, and the brain and have been shown to have a causative role in anxiety-like behavior." (PMID 35216112, 2022). "Moreover, IL‐6 has been shown to induce a primed transcriptional profile in monocytes recruited to the brain associated with the development of anxiety following psychosocial stress in mice (Niraula, Witcher, Sheridan & Godbout, 2019)." (PMID 31421056, 2021). "Additionally, the anxiety of spouse/partner relationships was significantly associated with IL-6/IL-10 ratios." (PMID 34360332, 2021).